ADAMTS8 (ADAM metallopeptidase with thrombospondin type 1 motif 8)
Diseases named in the same sentence as ADAMTS8 in open-access papers (continued):
Sharing a sentence is not in itself a finding about the gene and the disease.
brain cancer (4 papers, 2016 to 2021). A primary or metastatic malignant neoplasm affecting the brain. "ADAMTS8 is downregulated in brain cancers and may play a role in brain tumorigenesis." (PMID 34638718, 2021).
brain tumors (4 papers, 2006 to 2025). "ADAMTS8 is significantly downregulated in brain tumors, including high-grade gliomas, and plays a role in inhibiting angiogenesis by affecting stromal-epithelial interactions and matrix composition." (PMID 40650042, 2025). "Expression of ADAMTS8 transcript using quantitative RT-PCR in human brain tissues showed that ADAMTS8 was down-regulated in brain tumors compared to normal brain tissue samples." (PMID 24213506, 2012). "The aim of this study was to investigate the expression of ADAMTS-8 in high-grade gliomas and other brain tumours, and compare this with the expression of other well-characterised angiogenesis related genes TSP1 and VEGF." (PMID 16570050, 2006). "Brain tumours: Hundred percent of cases showed lower expression of ADAMTS-8 compared with normal brain." (PMID 16570050, 2006). "Methylation-specific PCR analysis of ADAMTS-8 indicated promoter hypermethylation in one out of 24 brain tumours (a metastasis) and three out of four glioma cell lines suggesting an alternative mechanism of downregulation." (PMID 16570050, 2006). "Overall the protein data for ADAMTS-8 suggest downregulation of the protein in the majority of brain tumours, although only further experimentation will determine the precise nature of this ADAMTS-8 protein." (PMID 16570050, 2006). "In summary, the RT–PCR data suggest that in contrast to TSP1 and VEGF, the downregulation of ADAMTS-8 is a consistent event in the formation of brain tumours and is consistent with findings in other cancer types." (PMID 16570050, 2006). "In contrast, we have shown that the expression of ADAMTS-8 is downregulated in brain tumours relative to normal brain." (PMID 16570050, 2006). "However, as yet, the possible role of ADAMTS-8 in brain tumour development remains unclear." (PMID 16570050, 2006). "ADAMTS-8 was not detectable in 14 out of 34 (41%) brain tumours, and downregulated between two- and a 1000-fold compared to normal brain in 21 out of 34 (62%)." (PMID 16570050, 2006). "Despite the downregulation of ADAMTS-8 mRNA and protein seen in the majority of brain tumours studied, there was no clear correlation between protein and mRNA expression levels." (PMID 16570050, 2006). "Moreover, immunohistochemical analysis revealed decreased levels of ADAMTS8 in 77% of brain tumors tested compared to non-neoplastic tissue, while this protein was undetectable in 67% of tumors in Western blot method." (PMID 34638718, 2021). "The mechanism of downregulation of ADAMTS-8 in these brain tumours is unknown, but seems unlikely to be hypermethylation of the promoter region as observed in 58% (29 out of 50) of NSCLC, since only one out of 24 tumours showed methylation using our assay." (PMID 16570050, 2006).
colorectal cancer (4 papers, 2018 to 2025). A primary or metastatic malignant neoplasm that affects the colon or rectum. "Specifically, ADAMTS8 has been identified as a potential tumor suppressor in colorectal cancer and is frequently silenced in carcinomas, including CRC, due to promoter methylation." (PMID 40650042, 2025). "ADAMTS8 usually functions as a tumor suppressor, as it has been found to be frequently downregulated in colorectal cancer." (PMID 38410799, 2024). "ADAMTS8 was shown to be differentially methylated in brain, thyroid, lung, nasopharyngeal, esophageal, gastric and colorectal cancers." (PMID 30081852, 2018). "Several in vitro and in vivo studies have shown that upregulation of ADAMTS8 could inhibit tumor growth in lung, breast, and colorectal cancers." (PMID 40650042, 2025). "Further investigation of the copy number variation of ADAMTS8 did not support this epigenetic regulatory mechanism in colorectal cancer linked to ADAMTS4." (PMID 35743687, 2022).
Hypertension (4 papers, 2017 to 2025). The presence of chronic increased pressure in the systemic arterial system. "NOS3 (fetal and maternal-acting), NRK (fetal), and ADAMTS8 (maternal-acting) have been implicated in placental function and hypertension." (PMID 39809772, 2025). "NOS3, NRK, and ADAMTS8 (fetal and maternal-acting) have been implicated in both placental function and hypertension." (PMID 38633783, 2024). "ADAMTS8 has been identified as a tumour suppressor gene in several types of cancers and single nucleotide polymorphisms (SNPs) in the ADAMTS8 locus have been associated with hypertension in a genome-wide association study (GWAS)." (PMID 33352066, 2020). "Therefore, our results suggest that the linear decrease in KLF2, HPX, TMEM8A, ADAMTS-8 and AP3S2 expression in the broiler kidney is directly or indirectly related to blood pressure, hypertension and weight gain." (PMID 28924246, 2017).
gastric cancer (3 papers, 2016 to 2025). A primary or metastatic malignant neoplasm involving the stomach. "ADAMTS8 hypermethylation is associated with decreased expression in gastric cancer and may play an important role in the invasion and metastasis of gastric cancer." (PMID 27493958, 2016). "However, further research focusing on the epigenetic silencing mechanism underlying the role of ADAMTS8 in gastric cancer is required." (PMID 27493958, 2016). "The result might indicate a possible association between ADAMTS8 and invasiveness of gastric cancer." (PMID 27493958, 2016). "The result might indicate a possible association between DNA methylation of ADAMTS8 and invasion and metastasis of gastric cancer." (PMID 27493958, 2016). "In a previous study, DNA methylation lowered the expression of ADAMTS8 to promote gastric cancer carcinogenesis." (PMID 35743687, 2022). "ADAMTS8 expression was lower in the gastric cancer cell lines SGC7901, MCG803, BGC823, and MKN45 compared to the normal gastric mucosa cell line GES1." (PMID 27493958, 2016). "We analyzed the expression and methylation of ADAMTS8 in primary gastric tumors and gastric cancer cell lines." (PMID 27493958, 2016). "In conclusion, our results demonstrate that expression of ADAMTS8 is significantly decreased and DNA methylation is frequent in gastric cancer." (PMID 27493958, 2016). "In our current work, we found that ADAMTS8 was downregulated in gastric cancer cell lines compared to normal gastric cells." (PMID 27493958, 2016). "The results showed that ADAMTS8 mRNA expression was significantly lower in the gastric cancer cell lines SGC7901 (0.85-fold), MGC803 (0.43-fold), BGC823 (0.19-fold), and MKN45 (0.13-fold) compared to the normal gastric cell line GES1 (1-fold as the control)." (PMID 27493958, 2016). "Moreover, ADAMTS8 expression was upregulated in the gastric cancer cell lines MGC803, BGC823, and MKN45 after treatment with 5-aza-2′-deoxycytidine." (PMID 27493958, 2016). "In addition, the effects of ADC treatment on ADAMTS8 DNA methylation status were assessed in the gastric cancer cell lines." (PMID 27493958, 2016). "Thus, our results demonstrate that expression of ADAMTS8 mRNA is significantly decreased and DNA methylation is frequent in gastric cancer." (PMID 27493958, 2016). "Furthermore, lower levels of ADAMTS8 mRNA in gastric cancer closely correlate with higher levels of gene methylation." (PMID 27493958, 2016). "Taken together, these findings suggest that hypermethylation may be an important mechanism in the inactivation of ADAMTS8 in gastric cancer." (PMID 27493958, 2016). "Since the expression of ADAMTS8 was downregulated in gastric cancer, we examined whether the gene was silenced by hypermethylation." (PMID 27493958, 2016). "However, an understanding of the precise mechanism of the downregulation of ADAMTS8 in gastric cancer needs to be further explored." (PMID 27493958, 2016). "Thus, in the present study, we examined ADAMTS8 expression in gastric cancer cell lines and tissue samples and investigated the epigenetic mechanisms responsible for the decreased ADAMTS8 expression in gastric cancer." (PMID 27493958, 2016). "This study provides evidence that ADAMTS8 may function as a tumor suppressor in gastric cancer." (PMID 27493958, 2016). "We treated four gastric cancer cell lines with demethylation agent ADC to inhibit DNA methylation and detected ADAMTS8 mRNA expression using qPCR analysis." (PMID 27493958, 2016). "We further analyzed ADAMTS8 methylation status in gastric cancer cell lines and two matched gastric tumors and nontumor tissues by BGS." (PMID 27493958, 2016). "We also found that ADAMTS8 expression was lower in gastric cancer tissues but broadly expressed in the nontumor tissues." (PMID 27493958, 2016). "The results indicated that ADAMTS8 mRNA expression was significantly lower in the primary gastric cancer tissues than in their corresponding nontumor tissues (0.247 ± 0.076 versus 0.881 ± 0.098; P < 0.001)." (PMID 27493958, 2016).
gastric cancer (continued). "We analyzed the methylation status of ADAMTS8 in gastric cancer cell lines, gastric cancer tissues, and corresponding nontumor tissues by MSP and BGS." (PMID 27493958, 2016). "In addition, ADAMTS8 mRNA expression was analyzed in 66 paired primary gastric cancer specimens and corresponding nontumor tissues by qPCR." (PMID 27493958, 2016).
glioma (3 papers, 2006 to 2025). A benign or malignant brain and spinal cord tumor that arises from glial cells (astrocytes, oligodendrocytes, ependymal cells). "The high expression of ADAMTS8 is associated with high survival, and its overexpression in glioma cells could inhibit cancer cell survival, invasion, migration, and tumor growth in vivo." (PMID 38460946, 2024). "For example, the expression of ADAM metallopeptidase with thrombospondin type 1 motif 8 (ADAMTS8) was found to be significantly diminished in glioma." (PMID 38460946, 2024). "Messenger RNA levels were reduced at least two-fold in 100% (34 out of 34) tumours and four out of four glioma cell lines tested, and protein data (IHC and Western) also suggested downregulation of ADAMTS-8." (PMID 16570050, 2006). "Despite the small number of cases, metastases and meningiomas were more likely to have lower ADAMTS-8 expression than gliomas (Mann–Whitney test: metastases P=0.013, meningiomas P=0.031)." (PMID 16570050, 2006). "Thus 70% GBM, 100% grade III gliomas, 100% meningiomas and 57% metastases showed decreased expression of the ADAMTS-8 protein compared to normal brain." (PMID 16570050, 2006). "However, before we can ascertain whether ADAMTS-8 and/or related molecules represent potential therapeutic targets in gliomas, further investigation of the ADAMTS gene family will be necessary to elucidate their potential roles relating to angiogenesis, ECM degradation and invasion." (PMID 16570050, 2006). "In ten tumours that showed vascular proliferation typical of high-grade gliomas on examination of the H&E sections, nine also showed up-regulation of both VEGF and TSP1, accompanied by at least eight-fold downregulation of ADAMTS-8." (PMID 16570050, 2006). "ADAMTS-8 was not detectable in three out of four meningiomas, four out of six metastases and four out of four glioma cell lines tested." (PMID 16570050, 2006). "The reduction in ADAMTS-8 expression was not tumour type specific, since 22 gliomas, four meningiomas, six metastases, one haemangioblastoma and one medulloblastoma were analysed." (PMID 16570050, 2006). "When analysed separately, both GBMs and grade III gliomas showed a significant downregulation of ADAMTS-8 compared to the non-neoplastic brain tissues (Mann–Whitney test: GBM P=0.001, grade III P=0.009)." (PMID 16570050, 2006).
pulmonary hypertension (3 papers, 2022 to 2024). Increased pressure within the pulmonary circulation due to lung or heart disorder. "Overexpression of ADAMTS8 was mainly discovered in PASMCs of PAH or mouse lungs of hypoxia-induced pulmonary hypertension." (PMID 38071234, 2023).
gastric tumors (2 papers, 2016 to 2023). "The data showed that methylation of the ADAMTS8 was detected in 60.6% (40/66) of gastric tumor tissues, and 39.4% (26/66) were unmethylated." (PMID 27493958, 2016). "ADAMTS8 mRNA expression was significantly lower in methylated primary gastric tumors." (PMID 27493958, 2016). "Methylation of the ADAMTS8 gene was statistically higher in primary gastric tumors than in nontumor tissues." (PMID 37240178, 2023). "Methylation of the ADAMTS8 gene was significantly higher in primary gastric tumors than in nontumor tissues (P = 0.024)." (PMID 27493958, 2016). "The methylation status of the ADAMTS8 was also examined in 66 primary gastric tumors and nontumor tissues by MSP." (PMID 27493958, 2016). "ADAMTS8 mRNA expression was significantly lower in primary gastric tumors with DNA methylation of ADAMTS8 than those without DNA methylation (P < 0.001)." (PMID 27493958, 2016). "We further found that methylation of the ADAMTS8 gene was significantly higher in primary gastric tumors than in nontumor tissues." (PMID 27493958, 2016).
glaucoma (2 papers, 2018 to 2022). Increased pressure in the eyeball due to obstruction of the outflow of aqueous humor. "In human genome wide association studies, loci near ADAMTS8 were found associated with IOP and vertical cup-disk ratio, which are important glaucoma endophenotypes, suggesting that ADAMTS genes are involved in human glaucoma." (PMID 30406200, 2018). "In humans, ADAMTS8 is associated with key glaucoma endophenotypes, suggesting a role for ADAMTS genes in human glaucoma." (PMID 36148008, 2022).
hepatocellular carcinoma (2 papers, 2020 to 2025). A malignant tumor that arises from hepatocytes. "In hepatocellular carcinoma, ADAMTS8 reduces cell proliferation and metastasis via the ERK pathway, with low expression indicating poor prognosis." (PMID 40650042, 2025). "ADAMTS8 could regulate invasion and apoptosis of hepatocellular carcinoma through ERK signaling pathway." (PMID 32296631, 2020).
keratoconus (2 papers, 2020 to 2023). A degenerative, structural disorder of the eye, characterized by a cone-shaped protrusion of the cornea. "Another missense variant p.(Gly236Glu) in heterozygosis was found in another gene coding for a metalloproteinase of the ADAMTS family, ADAMTS8 (OMIM: #605175), which has been described to be associated with central corneal thinning and keratoconus." (PMID 37895187, 2023).
osteoarthritis (2 papers, 2021 to 2025). A noninflammatory degenerative joint disease occurring chiefly in older persons, characterized by degeneration of the articular cartilage, hypertrophy of bone at the margins and changes in the synovial membrane. "Indeed, ADAMTS8 expression in cartilage is not significantly altered in murine models of osteoarthritis as would be expected if ADAMTS8 is critically involved in aggrecan turnover." (PMID 34687701, 2021).
abdominal aortic aneurysm (1 paper, 2021). Enlargement and ballooning of the vessel that supplies arterial blood to the abdomen, pelvis and legs. "Prior studies have described upregulation of ADAMTS8 in the macrophages of patients with abdominal aortic aneurysms." (PMID 34469433, 2021).
aortic aneurysm (1 paper, 2020). A ruptured aneurysm located in the wall of the proximal portion of the descending aorta proceeding from the arch of the aorta. "In patients with peripheral arterial occlusion, levels of ADAMTS8 and macrophages in the blood are lower if an aortic aneurysm is present." (PMID 32095376, 2020).
Arthritis (1 paper, 2009). Inflammation of a joint. "ADAMTS-5 was found to be the dominant aggrecanase in mouse models of arthritis, and a recent report indicates that ADAMTS-8, -15, -16, and -18 are expressed at very low levels in mouse cartilage." (PMID 19919704, 2009).
breast invasive ductal carcinoma (1 paper, 2020). "ADAMTS8 was related with poor prognosis for breast invasive ductal carcinoma patients." (PMID 32296631, 2020).
cervical cancer (1 paper, 2024). A primary or metastatic malignant neoplasm involving the cervix. "Common cell adhesion molecules, such as MMP1 and ADAMTS8, are reported to be associated with invasive metastasis of cervical cancer and to reduce patient prognosis." (PMID 38410799, 2024). "In our study, we observed a significant difference in the expression level of ADAMTS8 after JQ1 treatment, and we speculated that JQ1 might affect the prognosis of cervical cancer by altering the expression status of ADAMTS8." (PMID 38410799, 2024).
coronary disease (1 paper, 2008). "This small region contains several genes of interest; for example, polymorphisms in SNX19 have been reported to be associated with coronary disease, while ADAMTS8 is involved in regulating angiogenesis." (PMID 19000322, 2008).
COVID-19 (1 paper, 2023). A disease caused by infection with severe acute respiratory syndrome coronavirus 2. "There was an increased deposition of collagen in COVID-19 lungs, with an early increased expression of genes linked to ECM orchestration and organization, such as Tolloid-like 2, ADAMTS8, and collagen III." (PMID 37964271, 2023).
dilated cardiomyopathy (1 paper, 2022). Cardiomyopathy which is characterized by dilation and contractile dysfunction of the left and right ventricles. "We compared ADAMTS8 expression in normal hearts obtained from healthy donors in traffic accidents and failing hearts obtained from patients with dilated cardiomyopathy (DCM) undergoing surgery." (PMID 35224040, 2022). "ADAMTS8 expression was significantly increased in patients with dilated cardiomyopathy; its expression myocardial infarction and TAC rat models was also increased, accompanied by increased expression of α-SMA and Collagen1." (PMID 35224040, 2022).
endometrial cancer (1 paper, 2023). Primary or metastatic malignant neoplasm involving the endometrium (mucous membrane that lines the endometrial cavity). "In the same study, serum levels of ADAMTS 8 were found to be decreased in patients with endometrial cancer compared with patients with benign endometrial pathologies." (PMID 36982551, 2023).
exfoliation syndrome (1 paper, 2010). An autosomal dominant disorder caused by mutations in the LOXL1 gene, encoding lysyl oxidase homolog 1. "Using a proteomic approach, ADAM-19, −21, and ADAMTS-8 were detected in the anterior lens capsules of patients with co-existing Exfoliation syndrome (XFS)." (PMID 21197111, 2010).
fibrosis (1 paper, 2022). the formation of excess fibrous connective tissue in an organ or tissue in a reparative or reactive process. "To explore the role of ADAMTS8 in cardiac fibrosis following injury, after rats were subjected to LAD artery ligation, we injected adenovirus carrying overexpressed ADAMTS8 and positive control adenovirus into the myocardium at multiple locations around the infarct border zone." (PMID 35224040, 2022).
glioblastoma (1 paper, 2022). The most malignant astrocytic tumor (WHO grade IV). "When utilizing the database from the CancerSEA, we found that low levels of ADAMTS8 enabled cancer cell invasion in glioblastoma multiforme (GBM)." (PMID 35743687, 2022).
heart failure (1 paper, 2022). Inability of the heart to pump blood at an adequate rate to meet tissue metabolic requirements. "Many studies have described the important role of ADAMTSs in cardiac fibrosis and heart failure, specifically ADAMTS8 playing a key role in cardiovascular disease." (PMID 35224040, 2022). "Immunofluorescence showed that ADAMTS8 and vimentin were significantly increased in patients with heart failure." (PMID 35224040, 2022). "Western blotting confirmed that the expression of ADAMTS8 was increased in patients with heart failure, and the production of α-SMA and type I collagen was also increased." (PMID 35224040, 2022). "This study systematically revealed the pro-fibrosis effect of ADAMTS8 in cardiac fibrosis and explored its potential role as a therapeutic target for the treatment of cardiac fibrosis and heart failure." (PMID 35224040, 2022).